MMP2 (matrix metallopeptidase 2)
Diseases named in the same sentence as MMP2 in open-access papers (continued):
Sharing a sentence is not in itself a finding about the gene and the disease.
tumor (continued). "The overexpression of MMP2 was reported previously in several cancer tissues, and the inhibition of MMP2 function by halofuginone resulted in significant reduction of vascular functionality, decreased vascular density and less tumor size in VHL PCC in vivo models." (PMID 23106811, 2012). "If this hypothesis is correct, circulating tumor cells should express MMP-2 whether they are circulating in blood or the bone marrow, and MMP-2 expression would permit the invasion of the endostium and therefore facilitate the formation of micrometastasis." (PMID 23227342, 2012). "In present work, we demonstrated that MMP-2 may promote the recruitment of αvβ3 integrin and regulate αvβ3 integrin-mediated tumor cell migration." (PMID 22848537, 2012). "TGF-β1 promotes tumor progression through the upregulation of MMP-2." (PMID 22992780, 2012). "To test our hypothesis, we utilized murine models of the osteolytic tumor-bone microenvironment in immunocompetent wild type and MMP-2 null mice." (PMID 22238668, 2012). "Collectively, these data support our overarching hypothesis that an osteoblast derived proteinase, MMP-2, is key for mediating for TGFβ activation and tumor survival in vivo." (PMID 22238668, 2012). "Tumor-associated macrophages play an important role in tumor progression due to production of several angiogenic factors, such as VEGF, IL-8, inflammatory cytokines (IL-1 and IL-10) and proteases (MMP-2 and MMP-9)." (PMID 23024650, 2012). "It has been shown that inhibition of p-ERK1/2 may lead to a reduction in the expression of MMP-2 and invasive ability of tumor cells." (PMID 22264292, 2012). "However, little is known about the effects of MMP-2 on αvβ3 integrin activity and αvβ3 integrin-mediated adhesion and migration of tumor cells." (PMID 22848537, 2012). "Our static adhesion assay showed that the inhibition of MMP-2 impaired the adhesion of tumor cells, suggesting that MMP-2 activity may regulate the adhesion of tumor cells." (PMID 22848537, 2012). "They observed a significant decrease in tumor growth accompanied by downmodulation of the nuclear factor-kappaB (NF-κB) expression and transcriptional activity, and consequently in significant inhibition of MMP-2 and MMP-9 expression." (PMID 22811704, 2012). "Since decreased tumor growth was observed in MMP-2 null mice, we next assessed whether there was a concomitant decrease in osteolysis in the MMP-2 null tumor-bone microenvironment." (PMID 22238668, 2012). "The results indicated that MMP-2 was recruited to the leading edge of invasive tumor cells before αvβ3 integrin during migration, implying that MMP-2 may regulate αvβ3 integrin recruitment." (PMID 22848537, 2012). "Moreover, it is well known that production of MMP-2 and MMP-9 in PCa cells is associated to tumor invasion and progression." (PMID 21489246, 2011). "Tumor cell derived MMP-2 or MMP-9 were reported to elicit secretion of soluble VEGF from the ECM." (PMID 22267953, 2011). "In addition, TGF-β is believed to promote tumor growth and invasion by sustaining GBM stem cells, promoting angiogenesis, and upregulating expression of molecules such as MMP-2, which are associated with tumor invasion." (PMID 22190972, 2011). "TIMP4 inhibits tumor progression by inhibiting cell matrix degradation by endopeptidase MMP-2." (PMID 21909426, 2011). "It has furthermore been suggested that its coordinate overexpression with MMP-1 and/or MMP-2 may have a synergetic effect in tumor progression." (PMID 20946664, 2010). "MMP-2 is one of the most important MMPs in the process of tumor invasion and metastasis." (PMID 20637122, 2010). "Moreover, it has been shown that Her2 overexpression is related with the invasion capacity of the tumor cells that is related partly with the up-regulation of MMP-2 and MMP-9 expression as well as proteolytic activity." (PMID 20482751, 2010).
tumor (continued). "To test this conjecture we allografted CIB1-KO mice with murine tumor cells that endogenously expressed either very low levels (B16 melanoma tumor cells) or very high levels (Lewis lung carcinoma cells) of MMP-2, as previously demonstrated by zymography analysis." (PMID 20804551, 2010). "Moreover, we provided mechanistic evidence that MKP-1 suppresses both tumour proliferation and metastasis via promoting mesenchymal-to-epithelial transition followed by the dampening of MMP-2 and CXCR4 activities." (PMID 20226009, 2010). "Specifically as MMP-2 serves to degrade ECM and basement membranes underlying tumor cell invasion and migration, we showed by using an invasion assay in vitro that STAT3 downregulated tumor cell lines exhibit significant decreased invasion capability when compared with control." (PMID 24281074, 2010). "In gastric cancer, expression of MMP-2 is strongly associated with tumour progression and lymph node metastasis." (PMID 20334687, 2010). "MMP-2 is a self-antigen secreted by many cells and involved, through the degradation of the extracellular matrix and basal membranes, in multiple physiological processes and in tumor progression." (PMID 20689590, 2010). "Many studies have verified that MMP-2 plays an important role in tumor invasion." (PMID 19995435, 2009). "Tumour-associated macrophages are known to contain many proangiogenic factors, such as VEGF, TNF-α, CXCL-8, bFGF and proteases such as MMP-2 and MMP-9." (PMID 19352388, 2009). "MMP-2 has been shown to be involved in tumor invasion in vitro." (PMID 18426555, 2008). "Blocking or down regulation of PTTG1 in tumors may result in suppression of tumor growth and metastasis through the related down regulation of MMP-2 expression and activity." (PMID 19014669, 2008). "MMP-2 plays an important role in regulating tumor metastasis." (PMID 18597698, 2008). "Almost all tumor cells were positive for MMP-2 and MMP-9 staining." (PMID 18983683, 2008). "In addition, microarray gene expression studies on whole HNSCC tumour samples have identified the overexpression of several MMPs including MMP-2." (PMID 18349846, 2008). "The results of real time PCR show that thalidomide could down-regulate MMP-2 and MMP-9 mRNA expression, suggesting that thalidomide can inhibit tumor growth via down-regulation of the MMP-2 and MMP-9 mRNA level." (PMID 18983651, 2008). "Furthermore, in our studies, we showed that tumor developed in nude mice on injection of HEK293 cells that constitutively express PTTG expressed high levels of both MMP-2 mRNA and protein, and MMP-2 activity." (PMID 17096843, 2006). "For example, MMP-2 does not show an association with tumour differentiation, stage, metastasis, or patients' prognosis." (PMID 17026740, 2006). "Because MT1-MMP is known to activate MMP-2, reduced tumor cell invasion and tumor growth demonstrated in coculture experiments with MT1-MMP null fibroblasts may in part result from a failure to activate pro-MMP-2." (PMID 16515711, 2006). "Our results demonstrate that blocking or down regulation of PTTG expression in tumors overexpressing PTTG may result in suppression of tumor growth and metastasis, through the down regulation of MMP-2 expression and activity." (PMID 17096843, 2006). "However, despite the potential influence of host MMPs, the tumor volume was still reduced in both experimental groups, suggesting that fibroblast derived MMP-2 and MMP-9 promote tumor cell growth in vivo." (PMID 16515711, 2006). "Blocking of function of PTTG or down regulation of its expression in tumors may result in suppression of tumor growth and metastasis, through the down regulation of MMP-2 expression and activity." (PMID 17096843, 2006). "Transfection with either custom or SMARTpool® siRNAs targeting MT1-MMP were capable of inhibiting MT1-MMP protein expression on Western blot, pro-MMP-2 activation on gelatin zymography, and tumor cell invasion of 3D collagen matrices in response to either LPA or S1P." (PMID 17156449, 2006).
tumor (continued). "MMP-2 is known to play an important role in the proteolysis of ECM which allows endothelial cells to migrate towards the angiogenic stimuli to form new blood vessels to nurture tumor cells to grow." (PMID 17096843, 2006). "Oppositely, MMP-2 level in plasma is higher in T2 and T3 CRCs than T4 tumours." (PMID 17026740, 2006). "Thus, loss of MT1-MMP consistently decreased the invasion or growth promoting influence of fibroblasts in vivo and in vitro and loss of MMP-2 and MMP-9 altered tumor growth with increasing complexity of the model system." (PMID 16515711, 2006). "Furthermore, in vivo and in vitro studies have shown that LPS can increase vascular permeability, tumour invasion as well as increase inducible nitric oxide synthase and MMP2 production, two factors known to play a role in metastasis." (PMID 15026813, 2004). "We conclude that serum MMP-2 appears to reflect tumour resorption, while serum TIMP-1 may mirror tumour expansion." (PMID 12698191, 2003). "In grade 2 and 3 tumours, MMP-2 correlated significantly with shortened RFS and overall survival." (PMID 14520459, 2003). "Matrix metalloproteinases, and in particular MMP-2, the most abundant gelatinase, may play an important role in MM tumour growth and metastasis." (PMID 12771921, 2003). "Active MMP-2 increases more than its proform in tumour tissue." (PMID 12085179, 2002). "With the high levels of active MMP-2 present in tumour, total inhibition seems therefore unlikely." (PMID 12085179, 2002). "However, it would be unjustified to conclude from this that the role of MMP-9 in tumour invasion and progression would be less important than that of MMP-2, which shows increased activation in tumour." (PMID 12085179, 2002). "Overexpression of MT1-MMP and enhanced MMP-2 protein activity may thus be induced in the process of tumour progression." (PMID 12085179, 2002). "Thus there is not only more MMP-2 present in tumour than in normal tissue, but the ratio active to proenzyme also increases substantially." (PMID 12085179, 2002). "There was however an increase in MMP-2/TIMP-2 ratio in tumour compared to normal." (PMID 11401321, 2001). "Therefore, the inhibition of MMP-2 is an effective strategy for preventing tumor cell metastasis." (PMID 40894070, 2025). "Furthermore, IVC suppresses the transcriptional activity of VE-cadherin, EphA2, MMP2/9/14, PI3K, and LAMC2, as well as the protein expression of VE-cadherin, EphA2, and MMP2/9, thereby blocking tumor cell adhesion, ECM degradation, and the maintenance of vascular-like structures in HCC." (PMID 41019994, 2025). "Furthermore, we found that the PLEKHA1-TACC2 fusion proteins could significantly promote tumor growth by inducing VM formation, which is caused by stabilizing EphA2 protein and upregulating the EphA2/AKT/MMP2 signaling pathway." (PMID 40615663, 2025). "In a preclinical model, combining hemoglobin-loaded liposomes with chemotherapeutic agents effectively reduced MMP-2 expression and attenuated tumor invasiveness, suggesting that the indirect modulation of MMP activity through combination strategies may have therapeutic potential." (PMID 41409250, 2025). "Additionally, COL1A1 and FBLN1 were previously used as markers for canine tumor or fibroblast cells, and MMP2 and DCN as markers of mesenchymal-like cells in human cancers, with the latter also being a top differentially expressed gene in our canine STS sample." (PMID 41208961, 2025). "Furthermore, MMP2 is critical for processes such as tissue repair and tumor invasion." (PMID 40421012, 2025). "MMPs (e.g., MMP-2, MMP-9) are involved in extracellular matrix degradation, with their overexpression linked to tumor invasion and metastasis, while TIMPs (e.g., TIMP-1, TIMP-2), as natural inhibitors of MMPs, may exacerbate disease progression when their expression is imbalanced." (PMID 40332776, 2025).
tumor (continued). "Additionally, the downregulation of oncogenes and cancer-associated genes, such as IL6, MMP2, and CCND2, may deprive the tumor cell of its growth advantage." (PMID 40043049, 2025). "Treatment with gefitinib at 0.3 μM resulted in a modest but statistically significant reduction in MMP-2 expression to approximately 0.9-fold (p < 0.001), suggesting a slight inhibitory effect on this matrix-degrading enzyme, which plays a critical role in tumor invasion and metastasis." (PMID 41401147, 2025). "During EMT in tumor cells, the expression of proteins that promote cell-cell adhesion, such as E-cadherin, is decreased, while the expression of mesenchymal markers, including vimentin, MMP-2, and MMP-9, is increased, thereby enhancing cell migration and invasion capabilities." (PMID 41194934, 2025). "Additionally, in gastric cancer the suppressive effects of kisspeptin on tumor invasion are believed to be mediated through downregulation of matrix metalloproteinases (MMPs), particularly MMP-9 and MMP-2, which are critical in tumor invasion and metastasis formation." (PMID 39199311, 2024). "miR-20b-5p could modulate vascular endothelial growth factor A (VEGFA) transcription by targeting hypoxia-inducible 4 factor 1-alpha (HIF1α), may act as a tumor suppressor by hindering MMP-2 expression, leading to cell cycle arrest, and also has a regulatory function in oxygen balance." (PMID 39188680, 2024). "In addition, specific physiological microenvironments based on tumor tissue, such as high doses of metal matrix protease-2 (MMP-2), abundant bio-endogenous glutathione (GSH) in tumors, etc., provide trigger points for responsive L-NDSs in the tumor site, compared to normal tissue." (PMID 38755645, 2024). "Interestingly, MMP-2 activation by membrane type-1-MMP potentially amplifies protease activity and combination with direct cleavage of substrate causes effective tissue degradation and enhances tumor invasion and metastasis." (PMID 39769454, 2024). "To evaluate whether melittin inhibits tumor cell invasion and metastasis by interfering with EMT progression, we examined the expression of EMT-associated proteins, including MMPs (MMP2, MMP9), E-cadherin, N-cadherin, Vimentin, and related regulatory protein, in both in vivo and in vitro models." (PMID 39519238, 2024). "MMP2, also referred to as type IV collagenase, is released in the form of an inactive proenzyme that, when activated by hydrolysis, may break down gelatin and other proteins in the extracellular matrix, which is crucial for tumor invasion and metastasis." (PMID 38049463, 2023). "Moreover, the activity of NF-κB in endometrial carcinoma promotes tumor cell migration, invasion, and metastasis via stimulation of Ras-related C3 botulinum toxin substrate 1 (Rac1), MMP-2, and MMP-9 transcription, and thus the basement membranes’ and ECM degradation, respectively." (PMID 36769226, 2023). "Interestingly, CDK6, another target of the hsa-miR-29a miRNA, was found to mediate the recruitment of the transcription factors c-Jun and Sp1 to the MMP2 promoter that positively enriched the angiogenic and fibrotic tumor microenvironment, as widely observed in TNBC (ER−) patient tissues." (PMID 36834918, 2023). "The researchers found that xenograft tumours from “double-hit” cell lines had increased MMP-2 and MMP-9 activity compared to tumours from “single-hit” cell lines, which could also account, in part, for the poor clinical outcome of HNSCC patients with the “double-hit” profile." (PMID 38203696, 2023). "Also, MMP-7 activation of pro-MMP-2 and -9 can facilitate tumor invasion." (PMID 37513440, 2023).
tumor (continued). "When HEKMs reached the tumour area, guided by binding to the EGFR-HER2 complex, the MMP-2 substrate was degraded (as confirmed through fluorescence energy transfer analysis), leading to the deformation of the nanorods into spheres, which aided deeper tumour penetration." (PMID 37048731, 2023). "In addition, compared with the model group, 20 mg/kg of erianin could dramatically restrain the tumor growth of tumor-bearing mice, and significantly reduced the level of MMP-2, -9, and IL-10 in the serum." (PMID 37608888, 2023). "Furthermore, CD44 could specifically interact with the PEX sequence of MMP14, activate MMP2, and regulate cell migration, suggesting that CD44 and MMP2 may be closely related to the tumor metastasis." (PMID 36192574, 2023). "In particular, matrix metalloproteinase‐2 (MMP‐2) gained considerable attention for its ability to degrade the extracellular matrix, facilitating detachment from primary tumors and migration to secondary tumor sites, thereby underscoring its critical role in cancer metastasis." (PMID 38064181, 2023). "In addition, the downregulation of CRIM1 and c-MET can affect the expression of MMP2/9 (matrix metalloproteinase 2/9, an enzyme active in the degradation of the extracellular matrix), thereby reducing the impact of matrix degradation products in the tumor microenvironment." (PMID 37894282, 2023). "However, the HIF-1α inhibitor 2-ME2 abrogated the increase in VEGFA, MMP2, and MMP9 induced by GSTZ1 deficiency in orthotopic mouse models, revealing that inhibition of HIF-1α with 2-ME2 substantially reversed tumor growth, MVD, and progression in Gstz1-KO mice." (PMID 37906252, 2023). "Besides, tumor cells can produce proteases, such as thrombin, cathepsin B, MMP‐2, and MMP‐14." (PMID 37719444, 2023). "This MMP–TIMP–integrin complex is believed to play a critical role in the regulation (maturation, anchoring, activation, and inhibition) of surface-bound and released active MMP-2, which factors may promote tumor invasion, metastasis, and angiogenesis in concert." (PMID 37394009, 2023). "Moreover, benefiting from the pericellular MMP‐2, the transformation location could be restricted and nanofibers would be assembled on the tumor cell membrane." (PMID 36793151, 2023). "Studies on tumor tissue fragments taken from patients before the initiation of treatment with cisplatin and vinorelbine and two weeks after the end of the treatment cycle showed a statistically significant decrease in MMP2 gene expression compared to the baseline." (PMID 37509417, 2023). "In addition, the carrier-free nanoplatform could be selectively triggered to release ICG and αPD-L1 by utilizing the tumor overexpressed MMP-2, thereby significantly enhancing the accuracy of αPD-L1-based checkpoint blockade therapy." (PMID 34987658, 2022). "Gefitinib is another tyrosine kinase inhibitor, and its combination with EGCG could enhance the inhibition of tumor migration and invasion by decreasing enzymatic activity of tyrosine kinase and the expression of MMP-2, and suppressing the phosphorylation of ERK, JNK, p38, and AKT." (PMID 36545470, 2022). "On the other hand, the bioactivity of lovastatin was recently found to reduce the expression of matrix metalloproteinase (MMP)-9 and MMP-2, as well as the suppression of the Ras isoprenylation, which could subsequently decrease the invasive ability of tumor cells." (PMID 36558925, 2022). "Our findings suggested that THBS2 might promote cancer progression by remodeling the tumor microenvironment, affecting CD47-mediated signaling pathways, activating the pro-tumor functions of a disintegrin and metalloproteinase with thrombospondin motifs, and enhancing MMP-2 expression." (PMID 35701829, 2022). "Thus, MMP2 plays an important role in tumor cells invasion and metastatic diffusion." (PMID 35209039, 2022).